DKK1 (dickkopf Wnt signaling pathway inhibitor 1)
Diseases named in the same sentence as DKK1 in open-access papers (continued):
Sharing a sentence is not in itself a finding about the gene and the disease.
myeloma (continued). "Some scholars found that multiple myeloma cells can phosphorylate cAMP-responsive element-binding protein (CREB) through p38 kinase under hypoxic conditions and drive CREB into the nucleus to activate DKK1 transcription." (PMID 36213576, 2022). "DKK-1 expression has also been reported to be elevated in HCC tissues, and DKK-1 is dysregulated in various other malignant tumors, such as pancreatic cancer, colorectal cancer, multiple myeloma, and chronic lymphocytic leukemia." (PMID 35269944, 2022). "Another in vivo study reported obvious anti-osteolytic effects of BHQ880 in the 5T2MM murine model of myeloma, with concurrent protection against 5T2MM-induced trabecular bone loss, but BHQ880 treatment to inhibit DKK1 did not reduce tumor burden." (PMID 35355709, 2022). "Regulating DKK1 expression by targeting hypoxia and CREB together may have therapeutic significance in the management of myeloma patients with chemoresistance and lytic bone disease." (PMID 33420361, 2021). "A Dkk1 vaccination study in a murine model of myeloma showed higher CD4+ and CD8+ T-cell immune activity and provided a strong rationale for using Dkk1 as a myeloma immunotherapeutic target." (PMID 33126517, 2020). "Similarly, a Dkk1 neutralizing antibody (BHQ880A, Novartis) has shown striking effects in multiple myeloma by increasing bone formation and inhibiting tumor growth both in vitro and in vivo." (PMID 33287247, 2020). "Furthermore, different anti-myeloma regimens are known to reduce DKK-1 serum levels in treatment responders, providing a basis for development of DKK-1-targeted antibodies for myeloma bone disease." (PMID 30544512, 2018). "To date, the influence of DKK-1 on various cancer types has been controversial: DKK-1 was down-regulated in colon cancer, whereas its expression is high in hepatoblastomas, Wilms’ tumor, and multiple myeloma." (PMID 28938611, 2017). "In human diseases, anti-DKK-1 antibodies are under investigation for smoldering myeloma (phase 2 trial) but not yet RA." (PMID 26785768, 2016). "A recent study demonstrated that the DKK1-Wnt-OPG/RANKL intracellular signaling pathway can mediate the balance between OBs and OCs, which has becomeone of the most important factors in the pathogenesis of multiple myeloma." (PMID 26659358, 2015). "The blockade of DKK-1 using neutralizing antibodies resulted in a decrease of both osteolysis and skeletal tumor growth in a severe combined immunodeficiency (SCID)-hu murine model of multiple myeloma." (PMID 26237142, 2013). "In addition to causing bone disease, inhibition of osteoblast differentiation by DKK1 may also promote MM growth, since mature osteoblasts can suppress myeloma growth, whereas immature osteoblasts express high levels of IL-6, a central growth and survival factor for myeloma plasma cells." (PMID 22363428, 2012). "DKK-1 protein expression was positive in 3 of the 5 primary CD138+ myeloma cells and negative in all the SCs from 4 patients with MM." (PMID 20846389, 2010). "All of these results mightily suggest that myeloma cells could promote expressions of LRP5/6 and Krm1/2 on SCs in coculture via DKK-1 secretion." (PMID 20846389, 2010). "Thus, we concluded that, compared with myeloma cells in the same BM milieu, the SCs overexpressed DKK-1 binding receptor in response to DKK-1, which results in their intracellular Wnt signaling inhibition." (PMID 20846389, 2010). "Compared with the myeloma cells in the same BM microenvironment, SCs from patients with MM overexpressed LRP5/6 and Krm1/2, and thus had higher affinity to DKK-1, contributing to the different response to DKK-1." (PMID 20846389, 2010). "We used recombinant His-DKK-1 fusion protein and FITC-labeled anti-His polyclonal antibodies to determine the expression and binding capacity of DKK-1 receptor protein on the surface of myeloma cells and SCs." (PMID 20846389, 2010).
myeloma (continued). "At baseline, serum BCMA correlated with serum paraprotein (r = 0.42) and serum DKK1 correlated with serum free light chains (r = 0.67); the longitudinal change in both biomarkers differed between International Myeloma Working Group (IMWG)-defined responders and non-responders." (PMID 36612090, 2022). "Park and his fellows designed a cyclized oligopeptide against DKK1-low density lipoprotein receptor-related protein (LRP) 5/6 interaction and found reduced tumor burden in results after treatment with it, as a high level of DKK1 often results in osteolytic bone lesions in multiple myeloma models." (PMID 30699924, 2019). "Because DKK1 has been demonstrated to be a pathologically essential and strong prognostic factor in several studies, including ours, DKK1 could be a potential candidate for a future preclinical study of anti‐DKK1 therapy in HCC, as described for myeloma and osteosarcoma." (PMID 29117471, 2018). "Interestingly, a therapeutic approach based on tumour vaccine therapy showed that stimulating autologous T cells from MM patients with DKK1 peptides as the immunogen was able to specifically target myeloma cells without affecting normal blood cells." (PMID 27367730, 2016). "In humans, DKK-1 level was higher in myeloma patients with than without bone osteolytic lesions." (PMID 26785768, 2016). "In line with this hypothesis, we show here that DKK1 expression is often low or undetectable in advanced myeloma and is absent in MM cell lines, which are generally derived from advanced extramedullary myeloma." (PMID 22363428, 2012). "DKK1, a novel protein that is not expressed in most normal tissues but is expressed in almost myeloma cells, could be a potentially important antigenic target for antimyeloma immunotherapy." (PMID 22481968, 2012). "The mechanism involved that DKK1 could be secreted by multiple myeloma cells and bone marrow mesenchymal stem cells, which inhibited the classical WNT pathway, impeding osteoblast maturation and bone matrix mineralization, leading to osteolytic lesions of multiple myeloma." (PMID 38744806, 2024). "One aspect we did not explore was circulating levels of DKK1 and SOST in both naïve and myeloma‐bearing conditions, and the influence of either single or combination strategies with anti‐LRP6 and anti‐DKK1 on these antagonists." (PMID 36987921, 2023).
osteoporosis (99 papers, 2007 to 2025). A condition of reduced bone mass, with decreased cortical thickness and a decrease in the number and size of the trabeculae of cancellous bone (but normal chemical composition), resulting in increased fracture incidence. "Despite the noted effectiveness of DKK-1 inhibitors in osteoporosis, concerns have been raised regarding the increased risk of malignancies due to increased Wnt signaling pathway activation; thus, their safety and efficacy in humans remain to be established." (PMID 40940800, 2025). "Among potential biomarkers of bone metabolism, the Wnt pathway antagonist, Dickkopf-1 (DKK-1), is of particular interest because of its potential to reflect a shift towards joint ossification or osteoporosis, but its diagnostic value needs validation." (PMID 39596285, 2024). "Anti-Dkk-1 antibodies can effectively alleviate osteoporosis symptoms caused by estrogen deficiency." (PMID 36979418, 2023). "Different work also demonstrated that, long-term treatment with teriparatide in postmenopausal women with osteoporosis, is associated with significant increases in serum Dkk-1 levels." (PMID 35054152, 2022). "A common skeletal disease characterized by low BMD and impaired microarchitecture, osteoporosis (especially postmenopausal osteoporosis) is closely associated with DKK1 expression." (PMID 35355709, 2022). "In osteoporosis patients, serum levels of DKK1 are negatively associated with bone mineral density in the femoral head and lumbar spine." (PMID 33916321, 2021). "The high circulating levels of Dkk1 and Sost cause a significantly low activity of Wnt/β-catenin signaling in BMMSCs of patients with osteoporosis or age-associated bone loss." (PMID 33655459, 2021). "DKK1 is implicated in bone development, the pathological remodelling of bone in both OA and osteoporosis and mediating inflammation-induced bone loss by inhibiting osteoblast differentiation." (PMID 34440106, 2021). "DKK1 is implicated in the pathogenesis of osteoporosis, which is reflected in increased DKK1 serum levels in postmenopausal women and the negative correlation between serum DKK1 and their BMD." (PMID 31477034, 2019). "Human global gene expression analyses have identified DKK-1 as a bone mineral density (BMD)-associated gene in postmenopausal women, and serum DKK-1 levels are inversely associated with BMD in osteoporosis." (PMID 28153008, 2017). "Current opinions on osteoporosis realized that DKK1 level was associated with the pathophysiology of postmenopausal osteoporosis, and with the inflammatory cytokines effects on bone mass." (PMID 28628652, 2017). "DKK-1 is increased in serum of thalassemic patients who have osteoporosis, and is associated with reduced BMD in the lumbar vertebrae and end of the radius." (PMID 26199898, 2015). "Prolonged duration of menopause and increased serum DKK-1 are important risk factors for the development and severity of osteoporosis." (PMID 23878759, 2013). "In our study, we focused on the effects of polymorphisms in CER1 and DKK1 genes, recently reported as important susceptibility genes for osteoporosis, on bone mineral density (BMD) and bone markers in osteoporotic women." (PMID 24138842, 2013). "The correlation observed between serum DKK1 and BMD of the lumbar vertebrae and femoral neck suggests that DKK1 is implicated, at least partially, in the pathogenesis of osteoporosis in postmenopausal women." (PMID 23878759, 2013). "DKK1 overexpression in osteoblasts causes osteopenia and inhibits fracture repair, while DKK1 activation in osteoblasts seems to participate in the pathogenesis of estrogen deficiency-mediated osteoporosis." (PMID 23878759, 2013). "In our study, we investigated the possible association of two important susceptibility genes for osteoporosis, DKK1 and CER1, that participate in Wnt and TGFbeta signaling pathways, respectively, and are known for their functional role in bone mass regulation." (PMID 24138842, 2013).
osteoporosis (continued). "However, across studies, reduced β-catenin activity and elevated levels of Wnt inhibitors such as DKK1 were repeatedly associated with higher osteoporosis risk and disease progression." (PMID 41282593, 2025). "Dickkopf-1 (DKK1) is a well-characterized Wnt inhibitor and component of the Wnt/β-catenin signaling pathway, and its dysregulation is associated with multiple abnormal pathologies, including osteoporosis, Alzheimer’s disease, diabetes, and various cancers." (PMID 40394415, 2025). "In addition, the treatment of osteoporosis with teriparatide is associated with increases in serum DKK1." (PMID 37841984, 2023). "This indicates that neutralizing the Dkk1 antibody or enhancing Wnt/β-catenin signaling could effectively improve osteoporosis caused by thalassemia." (PMID 36979418, 2023). "Dickkopf-1 (DKK1) is a well-characterized Wnt inhibitor and component of the Wnt/β-catenin signaling pathway, whose dysregulation is associated with multiple abnormal pathologies including osteoporosis, Alzheimer’s disease, diabetes, and various cancers." (PMID 35355709, 2022). "Accordingly, an approach blocking Dkk1 as well as sclerostin might be the most effective strategy to counteract bone loss in cases of severe osteoporosis." (PMID 33479403, 2021). "Thus, in the Gzmb-HBZ mouse model, expression of PTHrP, RANKL and DKK1, known inducers of hypercalcemia and bone loss and therapeutic targets for osteoporosis and cancer, were increased in T cells." (PMID 29050201, 2017). "Given that many cases of MGUS also have osteoporosis and osteopenia, this may indicate that Wnt dysregulation and DKK1 overexpression are associated with early osteopenia in those patients and are potentially predictors of the development of osteolytic lesions." (PMID 36396631, 2022). "DKK1 is an endogenous inhibitor of the Wnt/beta-catenin signalling pathway and is implicated in bone development and in the pathological remodelling of bone in both OA and osteoporosis and mediating inflammation-induced bone loss by inhibiting osteoblast differentiation." (PMID 33916321, 2021). "Notably, patients with osteoporosis or age-associated bone loss display a significantly low activity of Wnt/β-catenin signaling in bone marrow mesenchymal stromal cells (BMMSCs), primarily due to the high circulating levels of Dkk1 and Sost." (PMID 33655459, 2021). "The effect of miR-203 on the osteogenic differentiation of MSCs in patients with osteoporosis, by inhibiting DKK1, was also studied." (PMID 39606935, 2025). "Anti-DKK1 antibody shows promise in osteoporosis treatment, as ovariectomized mice and rhesus macaques displayed a significant increase in BMD after receiving an anti-DKK1 neutralizing antibody." (PMID 40149867, 2025). "The action of LRP5 on bone is mediated via DKK-1 antagonism of the Wnt pathway; hence, in osteoporosis, several antibodies targeting DKK-1 have been designed and tested in animal models, demonstrating excellent results." (PMID 40940800, 2025). "Single nucleotide polymorphisms in genes critical for bone homeostasis, including ALPL, DKK1, PHEX, and COL1A1, are associated with osteoporosis and related skeletal pathologies in humans." (PMID 40961770, 2025). "miR-203 can promote the expression of osteogenic marker molecules and inhibit the expression of adipogenic marker molecules by targeting and downregulating DKK1, thereby regulating the dynamic balance between osteogenesis and adipogenesis in osteoporosis." (PMID 39606935, 2025). "The mice underwent various procedures to simulate different forms of osteoporosis, including genetic modification, ovariectomy, surgical interventions, administration of dexamethasone sodium phosphate, or treatment with Dkk-1." (PMID 41282593, 2025). "The overexpression of miR-203 significantly downregulated the expression of DKK1 in patients with osteoporosis, while the downregulation of miR-203 produced the opposite trend." (PMID 39606935, 2025).
osteoporosis (continued). "Elevated levels of DKK-1 have been associated with improved BMD, microarchitecture, and strength in postmenopausal women with osteoporosis." (PMID 41367909, 2025). "DKK1 has been found to be increased in postmenopausal women, which correlates with the severity of osteoporosis." (PMID 40430554, 2025). "Our findings suggest that long non‐coding RNA H19 mediates BMSCs' osteogenic differentiation in osteoporosis after SCI through the miR‐29b‐3p/DKK1 axis and by directly inhibiting the β‐catenin signalling pathway." (PMID 38685675, 2024). "In conclusion, the pathophysiology of osteoporosis following SCI is significantly influenced by the H19/miR‐29b‐3p/DKK1 axis." (PMID 38685675, 2024). "Compared with traditional anti-resorption drugs, anti-SOST antibodies, and anti-Dkk-1 antibodies can effectively increase bone formation and reverse the decline of bone mineral density in osteoporosis patients." (PMID 36979418, 2023). "After Zoledronic acid treatment, Dkk-1 concentration in serum was obviously decreased, and bone mineral density was remarkably increased in osteoporosis patients." (PMID 36979418, 2023). "In rheumatoid arthritis (RA) patients, hyperparathyroidism has been associated with cortical erosions, low bone formation, and secondary osteoporosis through overexpression of DKK-1." (PMID 37841984, 2023). "DKK-1 operates as an antagonist to the Wnt/β-catenin signaling pathway, and the use of antibodies targeting DKK-1 shows potential for the treatment of osteoporosis." (PMID 37511813, 2023). "The Wnt classical pathway inhibitors, such as sclerostin antibodies and dickkopf 1 (DKK1), have shown clinical potential for the treatment of osteoporosis." (PMID 38033331, 2023). "Pharmacological inhibition of sclerostin and DKK-1 by monoclonal antibodies is one of the novel therapy for osteoporosis that is capable to promote new bone tissue growth." (PMID 37703870, 2023). "To date, several genome-wide association studies (GWASs) have found hundreds of candidate genes associated with osteoporosis, including RANKL, SOST, ESR1, PTHLH, and DKK1." (PMID 37683138, 2023). "Due to a better understanding of the pathogenesis of osteoporosis, new treatments have been developed, such as anti-sclerostin, anti-DKK1 treatment, and analog of PTH-related protein." (PMID 35163300, 2022). "Pharmacological inhibition of sclerostin and DKK-1 by monoclonal antibodies has been explored as a potential therapy for osteoporosis, fracture healing, and other bone disorders." (PMID 36506070, 2022). "Meanwhile, DKK-1 is a suppressor of Wnt signaling and can inhibit bone formation leading to osteoporosis, and antagonizing DKK-1 can increase bone mass." (PMID 36188607, 2022). "The strongest correlations in our study were present between TH T-score and BMD and DKK1 gene expression in the group with advanced osteoporosis." (PMID 33357212, 2021). "The levels of DKK1 were significantly higher in postmenopausal women with osteoporosis compared to healthy controls." (PMID 32155909, 2020). "The upregulation and increased secretion of DKK1, a well-known biomarker of osteoporosis, is an important finding given it normally inhibits osteogenesis and promotes adipogenesis." (PMID 30837642, 2019). "This information is mandatory as anti-sclerostin and anti-DKK1 monoclonal antibodies emerge as very promising pharmaceuticals in the treatment of osteoporosis." (PMID 28493902, 2017). "Taken together, these observations indicate that systemic IL-32γ is negatively related with changes in DKK1 levels with the development of osteoporosis." (PMID 28079119, 2017). "Nevertheless, according to the already well-defined role of DKK-1 in bone homeostasis, patients with increased serum DKK-1 level are at risk of osteopenia or osteoporosis." (PMID 26785768, 2016). "A Dkk1-neutralizing antibody is in clinical trials for MM, and sclerostin-neutralizing antibodies have been developed for osteoporosis." (PMID 25757219, 2014).